STAT3 (signal transducer and activator of transcription 3)
Diseases named in the same sentence as STAT3 in open-access papers (continued):
Sharing a sentence is not in itself a finding about the gene and the disease.
breast tumor (continued). "On one hand, YHD inhibited the growth of 4T1 breast tumors via decreasing the number of MDSCs in the tumor microenvironment and through specific mechanisms associated with the downregulation of the expression of iNOS, ARG-1, IL-6, TGF-β, and p-STAT3." (PMID 30581487, 2018). "The IL-6/JAK/STAT3 feedback loop has been well documented in breast tumor growth and metastasis." (PMID 29934528, 2018). "Furthermore, MEG2 dephosphorylated STAT3 at Y705 in a time- and dose-dependent manner, and the inactivation of STAT3 resulted in decreased breast tumor growth." (PMID 30208623, 2018). "Moreover, Stat3 is responsible for mediating the effect of IL-6 on CSC maintenance in human breast tumor cells." (PMID 30004423, 2018). "Importantly, IL-6 can induce EMT through the STAT3 signaling, and its level increases with higher breast tumor grade and correlates with metastasis and poor patient survival." (PMID 29088851, 2017). "Finally, the ability of diminished tyrosine kinase signalling to initiate STAT1-driven immune surveillance can be overcome by compensatory STAT3 hyperactivation in breast tumours." (PMID 28276425, 2017). "Our data indicate that inhibition of pY239/240-ShcA-dependent STAT3 signalling may represent an attractive therapeutic strategy to sensitize breast tumours to multiple immunotherapies." (PMID 28276425, 2017). "Furthermore, PLK4-driven centrosome amplified breast tumour cells are highly sensitive to Stat3 inhibitors." (PMID 28474672, 2017). "We next interrogated whether our gene signatures could stratify STAT1 or STAT3 transcriptional responses in human breast tumours." (PMID 28276425, 2017). "Analysis of 965 primary breast tumors from TCGA RNA‐seq dataset showed that breast tumors harboring H1047R and other PIK3CA mutations (including E545K and E542K) have significant upregulation of AXIN2, HGF, STAT3, IGF‐1, and IGF‐2 mRNA compared with PIK3CA‐wild‐type and HER‐2‐amplified tumors." (PMID 28296140, 2017). "Moreover, the data also delineate molecular association of resistin and IL-6 at the regulatory level and establish STAT3 as a vital mediator in conferring the phenotypic response of resistin in breast tumor cells." (PMID 25868978, 2015). "GRN was positively correlated with an average of 42.9% of genes in STAT3 signatures but with an average of only 13.5% of genes in MYC signatures, supporting the preferential association of GRN expression with signatures indicative of functional STAT3 activation in primary breast tumors." (PMID 26000098, 2015). "Our results suggest that a combined treatment of STAT3 inhibitor with Herceptin may help overcome the incurred resistance derived from the enriched cancer stem-like cells in breast tumors." (PMID 24297508, 2014). "We observed the phosphorylated STAT3 expression from these breast tumors by immunohistochemistry." (PMID 24297508, 2014). "Our study suggests STAT3-NF-kB-hTERT signaling axis may provide a novel target-therapy for cancer progression and metastasis in human breast tumors." (PMID 24386318, 2013). "Our findings that even after exhaustive Rac inhibition in intact breast tumour, STAT3 activity is detected in rare live cells suggest that optimal treatment may require a combination of drugs inhibiting Rac and STAT3 activities." (PMID 22689141, 2012). "Then, we confirmed our IHC findings using immunofluorescent staining of a primary patient breast tumor and found that cells with p-TrkA were also positive for p-STAT3, supporting our hypothesis that these two proteins are co-expressed and co-localized in breast tumor tissues." (PMID 34066153, 2021). "Similarly, 83% of HER2-positive breast tumors were highly stained for both p-TrkA and p-STAT3." (PMID 34066153, 2021). "Notably, increased expression levels of IL-6 and p-STAT3 have been detected at the leading edge of breast tumors and linked to advanced disease, suggesting a mechanistic role of the JAK/STAT cascade in promoting breast tumor progression." (PMID 29934528, 2018).
breast tumor (continued). "They further suggest that the STAT1/STAT3 ratio is dynamically regulated in individual human breast tumours and support the potential for utilizing this ratio to predict intrinsic immune surveillance and sensitivity of breast tumours to specific immunotherapies." (PMID 28276425, 2017). "The liposomes increased STAT3 expression in HS cells, while they reduced NRF2 and STAT3 in HSD cells, suggesting beneficial effects on Dox-resistant breast tumor cells." (PMID 42072066, 2026). "Mechanistically, MDSCs in the breast tumor microenvironment promote invasion and metastasis via pathways such as STAT3-NF-κB-IDO, STAT3/IRF-8, and PTEN/Akt, involving both inhibitory and stimulatory cytokines." (PMID 40909271, 2025). "In this model system, we have identified key regulatory roles for STAT3 and of p65 activation in controlling TME Stimulation-driven pro-metastatic effects in HR+/HER2− breast tumor cells." (PMID 37190183, 2023). "Given the important role of tumor-cells–macrophages interaction on tumor growth, Phillip and colleagues investigated the STAT3 activators and EGFR agonists secreted by tumor-primed monocytes and MΦ and their impact on breast tumor growth." (PMID 34207035, 2021). "Recent data have shown that the JAK2/STAT3 pathway is preferentially activated in CD44 + CD24- breast CSCs through the excessive production of IL6 and promotes CSC growth in breast tumors." (PMID 31511084, 2019). "Impressively, for doxorubicin-induced senescent breast tumor cell line MDA-MB-231, Rh2 not only suppressed the accepted p38MAPK and NF-κB pathways but also prohibited Stat3 pathway." (PMID 30871042, 2019). "YLL545 inhibited breast tumor growth and angiogenesis by blocking VEGFR2-mediated downstream signaling pathways, such as STAT3 and ERK1/2." (PMID 27203384, 2016). "A number of studies have demonstrated that STAT3 inhibitors, including cepharanthine, niclosamide, cryptotanshinone and JSI124, suppress breast tumor growth." (PMID 25013518, 2014). "To explore this we examined the inhibitory effects of two STAT3 inhibitors, LLL12 and Stattic as well as STAT3 ShRNA on breast tumor initiating cells." (PMID 24376586, 2013). "Results showed that node-positive triple-negative breast cancer (TNBC) and HER2-positive breast tumors highly co-express p-TrkA and p-STAT3Of the nine TNBC samples, we found that 100% of them have high p-STAT3 and 77.8% of these samples concurrently express high p-TrkA." (PMID 34066153, 2021). "STAT3, STAT5, and STAT6 are strongly activated in breast tumors and act as mammary oncogenes." (PMID 34090412, 2021). "Most focus on STAT3 signalling is centred on pY705STAT3, the transcription-promoting form of the protein, which drives many adverse cancer features such as epithelial-mesenchymal transition in HER2-positive breast tumours." (PMID 32797246, 2021). "Leptin enriched in mammary adipocytes could downregulate CD8+ T cell effector functions through activating STAT3-FAO and inhibiting glycolysis, leading to inhibition of breast tumor development." (PMID 32787888, 2020). "In contradistinction to the previous report that used cell lines, we establish that STAT3, not Wnt signaling, is the primary target mechanistically responsible for endocrine resistance of breast CSCs in human breast tumors." (PMID 32472077, 2020). "STAT3 was first described to be constitutively active in invasive, but not benign, breast tumour biopsies." (PMID 29875329, 2018). "Our results showed that The mechanisms of YHD inhibit 4T1 breast tumor growth may be related to downregulating the expression of iNOS and ARG-1, negatively regulating the Janus kinase/STAT3 (JAK/STAT3) pathway by repressing the expression of IL-6 and TGF-β." (PMID 30581487, 2018). "However, it is worth noting that to our knowledge this is the first time that promoter methylation in CCDC8, HOXD3, PCDH8, PENK, STAT3, SFRP2 and WIFI has been described in primary breast tumours." (PMID 26052355, 2015).
breast tumor (continued). "It is reasonable to think that for breast tumors containing constitutive STAT3 activity but lacking STAT5 activity, STAT5 could be activated through therapeutic intervention." (PMID 40507264, 2025). "Furthermore, the activity of Chol-siRNA polyplexes against STAT3 mRNA in primary 4T1 breast tumors has not been determined or as thoroughly characterized as Chol-DsiRNA polyplexes." (PMID 35076584, 2022). "However, it has been proved that Fe not only works fundamentally in many pathophysiological functions but also participates in the occurrence of breast tumors by interfering with signalings, such as VEGF, ROS, MAPK, and IL-6/JAK2/STAT3 signaling in animal models." (PMID 35782923, 2022). "We chose an equimolar dose of Chol-siSTAT3 [0.41 mg/kg] and Chol-DsiSTAT3 [0.5 mg/kg] that does not maximally suppress STAT3 mRNA in primary 4T1 breast tumors to eliminate possible effects of tumor dose saturation on the kinetics of mRNA suppression in the primary tumor." (PMID 35076584, 2022). "However, the mechanism by which ROS activates Stat3 in BM-MSCs in response to breast tumor-mimicking conditions and the mechanism by which ROS and JAK/Stat3 increase HIF-1α expression remain unclear and must be further investigated." (PMID 36230633, 2022). "By using gene expression profiling of primary breast tumors either expressing or lacking pStat3 protein, we identified a number of potential Stat3 target genes which may be involved in metastasis including ENPP2 (ATX)." (PMID 22140473, 2011). "To define whether STAT3 directly regulates Kat2a expression we next performed ChIP-qPCR in 4T1 and EMT6.5 breast tumor spheroids with and without extra palmitate." (PMID 41826695, 2026). "Furthermore, STAT3 and IL5 but not GM-CSF were differentially expressed between breast tumor tissue and normal tissue (p value = 2.5 × 10−3, 4.5 × 10−4 and 0.63, respectively)." (PMID 26621531, 2016).
atherosclerosis (141 papers, 2008 to 2026). A disease characterized by the build-up of fatty material and calcium deposition in the arterial wall resulting in partial or complete occlusion of the arterial lumen. "STAT3 has been implicated in various cardiovascular conditions, including atherosclerosis, myocardial fibrosis, and other related disorders." (PMID 40166646, 2025). "Based on network pharmacological analysis, the potential targets of AATP for atherosclerosis (AS) therapy include STAT3 and the JAK/STAT pathway, which are associated with inflammatory responses." (PMID 40647133, 2025). "Activation of the JAK2/STAT3 pathway is strongly linked to the IL‐6 cytokine family, which plays a critical role in endothelial cell dysfunction associated with atherosclerosis." (PMID 40166646, 2025). "We previously found that PIAS3 was negatively associated with the JAK2/STAT3 activation and inflammatory responses in macrophages during atherosclerosis." (PMID 37008329, 2023). "The JAK2/STAT3 pathway is intimately linked to the IL-6 cytokine family, which plays a critical role in endothelial cell dysfunction during atherosclerosis." (PMID 35607519, 2022). "Among them, CD36, CDC42, JAK2, and STAT3 proteins were closely associated with atherosclerosis and foam cells, and their protein expressions were opposite to those of the ox-LDL group and converged with those of the control group after the sinapine base intervention." (PMID 36903257, 2023). "Thus, Th22 cell‐derived IL‐22 aggravates atherosclerosis development through a mechanism that is associated with IL‐6/STAT3 activation, DC‐induced Th17 cell proliferation and IL‐22–stimulated SMC dedifferentiation into a synthetic phenotype." (PMID 32022386, 2020). "It suggests that ruxolitinib may attenuate atherosclerosis by inhibiting JAK2/STAT3/SOCS3 signaling pathway, while the detailed underlying mechanisms still need further studies." (PMID 32169038, 2020). "Notably, activation of the JAK2/STAT3 pathway is closely associated with the IL-6 cytokine family, which plays an essential role in endothelial cell dysfunction during atherosclerosis." (PMID 31588227, 2019). "Mech­anistically, the protective effect of OSMR-β deficiency on atherosclerosis may be partially attributed to the inhibition of the JAK2/STAT3 activation in macrophages, whereas OSM stimulation can activate the signaling pathway." (PMID 28258089, 2017). "Notably, STAT3 activity is commonly associated with detrimental effects in atherosclerosis." (PMID 37828508, 2023). "STAT3 directly interacts with the nicotine receptor nAChRα1 to regulate the nuclear translocation of STAT3 and its binding to the Akt promoter region, thereby promoting the proliferation and migration of VSMCs and inflammation mediated by macrophages, which in turn causes atherosclerosis." (PMID 34513948, 2021). "The anti-inflammatory effects of the JAK2/STAT3 pathway in the context of atherosclerosis were also reported." (PMID 39936945, 2025). "Conversely, application of a STAT3 inhibitor has been shown to alleviate atherosclerosis by suppressing endothelial dysfunction, macrophage differentiation and CD4+ T effector activation." (PMID 41423554, 2025). "In vitro experimental results indicate that glycoside combinations of Buyang Huanwu decoction ameliorated atherosclerosis by inhibiting STAT3, HIF-1, and VEGF." (PMID 40478326, 2025). "Galangin exerts multi-target anti-inflammatory and endothelial protective effects in ameliorating the progression of atherosclerosis by modulating the miR-124/STAT3 axis." (PMID 40242436, 2025). "By applying transcription analysis to study the Shexiang Baoxin pill (SBP) in atherosclerosis treatment, key target genes (MAPK3, AKT1, and STAT3) associated with the prescription’s efficacy were identified." (PMID 41282606, 2025).
atherosclerosis (continued). "The STAT3 pathway is strongly related to atherosclerosis, and activation of the STAT3 pathway is critical for the effects of endothelial cell function, macrophage polarisation responses, inflammation, and immune responses." (PMID 40165931, 2025). "Previous studies have found that HDAC1/2 promotes arterial endothelial cell surface vascular cell adhesion molecule-1 expression and atherosclerosis through inhibition of STAT3 acetylation-dependent GATA6 promoter methylation." (PMID 38444939, 2024). "Our research illustrates that quercetin inhibits the KLF4-mediated phenotypic switch of VSMCs to macrophage-like cells and reduces atherosclerosis by suppressing the JAK2/STAT3 pathway." (PMID 39062998, 2024). "The results revealed that, compared to the ND group, the HFD group exhibited conspicuous co-localization of α-SMA+CD68+KLF4+, α-SMA+CD68+p-JAK2+, and α-SMA+CD68+p-STAT3+ at the foam cell aggregation regions of atherosclerosis plaque-rich aortic." (PMID 39062998, 2024). "LXN-deficient macrophages enhance cholesterol efflux by activating the STAT3/ATP-binding cassette transporter pathway, thus inhibiting the formation of foam cells and atherosclerosis." (PMID 39424784, 2024). "It has been noted that HDAC1 can be involved in VCAM-1 expression and promotion of atherosclerosis through inhibition of STAT3 acetylation-dependent methylation of the GATA6 promoter." (PMID 37405052, 2023). "An increasing number of studies have demonstrated that the JAK2/STAT3 signaling pathway is strongly activated when modulating atherosclerosis, including endothelial cell dysfunction, macrophage polarization, inflammation and immunity." (PMID 37237975, 2023). "Raloxifene, a STAT3 phosphorylation inhibitor, protects against high-fat-induced atherosclerosis in ApoE−/− mice and rabbit." (PMID 36807553, 2023). "As expected, we found that JAK2 and STAT3 levels of rats in the diabetic atherosclerosis group were negatively correlated with 25(OH)D concentrations and significantly decreased after vitamin D intervention." (PMID 35082965, 2022). "IL-1β was evidentially upregulated, while STAT3 was significantly downregulated in the atheroma plaque group, which indicated potential key roles for both in atherosclerosis progression." (PMID 36456628, 2022). "Characterisation of macrophages from human carotid artery plaques and in vitro assays reveal that macrophages regulate vascular smooth muscle cell function during atherosclerosis progression through the IL-1β/STAT3 axis." (PMID 36456628, 2022). "The current findings provide interesting insight into the macrophages-macrophage-like VSMC crosstalk, which would drive functional alterations in the latter cell type through IL-1β/STAT3 axis during atherosclerosis progression." (PMID 36456628, 2022). "Based on its translocation, STAT3 can be classified as nuclear or mitochondrial, and both are thought to play essential roles in the development of atherosclerosis, including endothelial cell malfunction, macrophage polarization, inflammation, and immunology." (PMID 35607519, 2022). "Various studies have shown that the activation of JAK2/STAT3 signaling pathway promotes the proliferation of VSMCs and involves in the progression of atherosclerosis by modulating apoptotic regulatory proteins such as B cell lymphoma-2 (Bcl-2) and cyclinD1." (PMID 35082965, 2022). "This is the first study to report the role of the IL-1β/STAT3 axis in the regulation of macrophage-like VSMCs during atherosclerosis progression." (PMID 36456628, 2022). "Inhibiting IL-6/STAT3 signaling pathway can protect against high-fat-induced atherosclerosis in ApoE (-/-) mice." (PMID 35783840, 2022). "Taken together, knockdown of lnc-KCNC3-3:1 alleviates the development of atherosclerosis via downregulation of JAK1/STAT3 signaling pathway." (PMID 34540913, 2021).